TFAM (transcription factor A, mitochondrial)
Diseases named in the same sentence as TFAM in open-access papers (continued):
Sharing a sentence is not in itself a finding about the gene and the disease.
tumor (continued). "In addition, the fold increase in the mtDNA level in recipient cells induced by tumor cell-derived EVs was not impaired by depletion of TFAM, a critical driver indispensable for mtDNA replication, excluding the possibility of endogenous induction." (PMID 38688896, 2024). "Moreover, TFAM‐related mitochondrial dysfunction was confirmed to further activate the downstream cGAS‐STING axis, which was well‐documented to function a suppression effect on OSCC and many other tumours." (PMID 39169452, 2024). "Additionally, in OPM-BMG tumors, the upregulated level of mitochondrial biogenesis regulatory proteins PGC-1α (~1.73 fold) and TFAM (~1.5 fold), compared to BMG-1, confirmed an increase in mitochondrial mass and the induction of mitochondrial biogenesis in OPM-BMG tumor tissue." (PMID 36591481, 2022). "Our results indicated that PGE2 could stimulate TFAM expression in tumor cells without being irradiated." (PMID 30862036, 2019). "Lack of both PGCα and TFAM was observed in nine tumours (17% of total cohort)." (PMID 25243473, 2014). "Here, out of the nine tumour samples that were double-negative for both PGC1α/TFAM, eight were CCC." (PMID 25243473, 2014). "However, the expression level of TFAM did not influence the proliferation rate of tumor cells." (PMID 41274938, 2025). "Similar to in vitro growth, significant larger TFAM-silenced OECM1- and HSC3-, but not SAS- and FaDu-, bearing xenografic tumours were detected in vivo, implying that TFAM expression is negatively associated with HNC cell growth." (PMID 34663785, 2021). "In MC, six tumours were positive and one was negative (66% and 34%, respectively), and in LGSC, the only tumour included expressed TFAM (100%)." (PMID 25243473, 2014).
cancer (78 papers, 2013 to 2026). A tumor composed of atypical neoplastic, often pleomorphic cells that invade other tissues. "For instance, TFAM expression was upregulated in colitis-associated cancer tissues and contributed to cell growth." (PMID 41362737, 2026). "One reported mechanism of mtDNA leakage in ATM-deficient murine cancer cells is via downregulation of the mitochondrial transcription factor A (TFAM)." (PMID 38084916, 2024). "have described that the reduction of mtDNA made by the mitochondrial transcription factor A (TFAM) mutation plays a potential role in cancer progression and resistance to cisplatin in MSI CRC." (PMID 36686736, 2022). "Mitochondrial transcription factor A (TFAM) is a protein that maintains mitochondrial DNA (mtDNA) integrity, and alterations in its expression are associated with mitochondrial damage and cancer development." (PMID 29747444, 2018). "Accordingly, mtDNA depletion would be a more effective therapeutic approach against TFAM-associated cancer." (PMID 29259235, 2017). "According to the data from the Genotype-Tissue Expression Project30, the cancer risk allele (G) of rs10826175 was associated with increased TFAM mRNA in various tissues, including the stomach and esophagus." (PMID 29259235, 2017). "However, no studies have specifically reported an association between lower TFAM expression and poor cancer cell differentiation." (PMID 41398603, 2025). "Previous studies indicate that TFAM deficiency may lead to increased production of ROS or apoptosis induction in cancer cells." (PMID 39580766, 2024). "It has also been reported that an unbalance in the mtDNA copy number due to TFAM alterations may be associated with many neurodegenerative and cardiac diseases, as well as cancer." (PMID 30845180, 2019). "Therefore, it is likely that the upregulation of TFAM is associated with increased cancer susceptibility." (PMID 29259235, 2017). "Therefore, a better understanding of the molecular mechanisms underlying the relationship between NSCLC tumorigenesis and TFAM expression will facilitate better approaches in cancer treatment." (PMID 26820294, 2016). "However, the roles of TFAM and certain miRNAs and their association in cancer development remain unclear." (PMID 24137381, 2013). "This study integrates pan-cancer bioinformatics analyses with experimental evidence to comprehensively elucidate TFAM's multifaceted impact on tumorigenesis." (PMID 41774266, 2026). "Despite its known physiological importance, TFAM plays a complex and often paradoxical role in cancer biology." (PMID 41774266, 2026). "We systematically investigated the heterogeneity of TFAM across diverse cancer types, specifically focusing on its regulatory mechanisms in metabolic reprogramming, signal transduction, and immune microenvironment remodeling." (PMID 41774266, 2026). "In conclusion, our findings provide compelling evidence that SIRT6 establishes a network linking nuclear and mitochondrial transcription through the regulation of TFAM, identifying TFAM as a potential therapeutic target for cancer." (PMID 41362737, 2026). "Based on TFAM’s critical role in mitochondrial biogenesis, our clinical observations appeared consistent with the Warburg effect in cancer progression, particularly through the lens of mitochondrial dysfunction associated with reduced TFAM expression." (PMID 41398603, 2025). "Dysregulation of TFAM not only contributes to the progression of malignant tumors, but also regulates the sensitivity of cancer cells to chemotherapeutic drugs, including cisplatin." (PMID 38429817, 2024). "The significant role of TFAM in tumors makes it a potential therapeutic target for cancer treatment, with modulating TFAM expression or activity holding promise for developing novel strategies to selectively target cancer cells." (PMID 38589371, 2024).
cancer (continued). "In accordance, ATF1 is positively correlated with both pluripotent (33/33, 23/33 of cancer types for MYC and NANOG, respectively) and mitochondrial regulators (33/33 of cancer types for both TFAM and NRF1) in TCGA cohorts." (PMID 37463926, 2023). "TFAM knockdown and overexpression in several cancer cell lines revealed that the relationships between TFAM knockdown or overexpression and mitochondrial biogenesis did not follow any particular pattern." (PMID 37372108, 2023). "It delves into the nanoscale mechanisms of OnB, elucidating their role in mitochondrial metabolism (TFAM, PGC1alpha), hypoxic responses (HiF-1alpha), and their interplay in chronic pathologies including cancer and neurodegenerative disorders, amongst others." (PMID 38063756, 2023). "The newly synthesized membrane phospholipids are required for mitochondrial fusion/fission, which adjusts the cancer cells to adapt to the decrease of mtDNA copy number after TFAM knockdown and influence cancer cell migration." (PMID 35163779, 2022). "To evaluate the consequences of decreased mtDNA copy number in human cancers, we have focused on the TFAM-mtDNA pathway in the past 10 or more years." (PMID 35163779, 2022). "TFAM is critical for mitochondrial DNA replication, transcription, and stability, which has been confirmed to be related with poor prognosis in several cancers." (PMID 35464857, 2022). "Nucleoids anchor mtDNA through mitochondrial transcription factor A (TFAM) binding and cancer cells often contain TFAM mutations." (PMID 35741087, 2022). "Even cancer cells show the same pattern, further confirming that TFAM levels and mtDNA copy number are directly related." (PMID 35054416, 2021). "VEGF enhances cancer cell proliferation by decreasing Akt-PGC1α-TFAM signaling-mediated mitochondrial biogenesis, ROS production, and cell apoptosis." (PMID 33628590, 2021). "Collectively, these findings provided an alternative scheme for development of TFAM/Akt-ERK combinational anti-cancer therapeutic strategy for HNCs." (PMID 34663785, 2021). "A more recent study showed that TFAM mediated regulations for oncogenicity in various cancers probably occur via the disruption of LC3-II-mediated autophagy." (PMID 34663785, 2021). "In certain types of cancer, TFAM binds to the promoters of apoptosis-related genes and regulates their expression." (PMID 33495511, 2021). "It has been reported that inhibition of TFAM led to increased sensitivity of cancer cells to cisplatin, doxorubicin, or ionizing irradiation." (PMID 32093281, 2020). "In the present study, we demonstrated that knockdown of TFAM retarded autophagy flux in cancer cells, which was similar to the finding that in lymphocytes, genetic deletion of TFAM restrained the formation of LC3-II." (PMID 32093281, 2020). "Together with our result, TFAM is a candidate target for increase the efficiency of cancer chemo‐ or radiotherapy." (PMID 31062473, 2019). "TFAM can be up-regulated by ionizing radiation in cancer cell lines, to decrease radiation induced cell death." (PMID 30862036, 2019). "Other studies addressed the relation between Krüppel-like (KLF) transcription factors, TFAM and cancer." (PMID 30845180, 2019). "For example, in breast MDA-MB-231, T47D, MCF-7, and MDA-MB-453 cancer cells, TFAM is involved in cell growth and metastasis progression." (PMID 31600993, 2019). "The increased expression of TFAM can be considered as a prognosis marker for poor clinical outcomes of specific type of cancer." (PMID 30862036, 2019). "Lowering the expression of TFAM in cancer cell lines resulted in cell cycle arrest at G1/S phase, attenuated cellular proliferation, enhanced DNA damage and cell killing levels by radiation." (PMID 31062473, 2019). "Han indicated that the over-expression of TFAM enhanced the growth of cancer cell lines, whereas the down-regulation of TFAM inhibited cell growth." (PMID 30862036, 2019).
cancer (continued). "It was pointed out that suppressing the expression of TFAM inhibited the proliferation of cancer cells, increased the sensitivity of cancer cells to chemotherapeutic drugs or ionizing irradiation, and triggered apoptosis." (PMID 30862036, 2019). "In breast MCF-7 cancer cells, mTOR activates mitochondrial biogenesis by increasing TFAM, mitochondrial ribosomal proteins, and some components of respiratory complex I (NDUFAF2, NDUFAF4, and NDUFS6) and ATPS (ATP5D, ATP5L, ATP5G1, ATP5O)." (PMID 31600993, 2019). "TFAM has been considered a potential target for cancer therapy since changes in its expression have been detected in several types of cancer." (PMID 29747444, 2018). "Regarding the regulation of mtDNA copy number, DNA polymerase gamma and TFAM should be emphasized in cancers." (PMID 27231905, 2016). "The high expression of TFAM has been reported to be related with a poor prognosis in multiple malignant tumors, including ovarian cancer, endometrial carcinoma and colon cancer." (PMID 24137381, 2013). "This study highlighted the critical role of PRDX6 in BRCA progression, particularly its ability to promote mitochondrial biogenesis and OXPHOS through both TFAM‐dependent and ‐independent pathways, thereby enhancing cancer cell proliferation, migration, and invasion." (PMID 40583735, 2025). "This suggests that HER2 may represent another molecular factor contributing to the context-dependent role of TFAM in cancer progression." (PMID 41398603, 2025). "These knowledge gaps highlight the broader need to define the functional consequences of mt epigenetic changes– including TFAM modifications, mtDNA methylation, and non‐coding RNA activity, particularly given their emerging roles in neurodegeneration, cancer, and metabolic diseases." (PMID 40418056, 2025). "In TFAM-deficient ESCC cells, ISGs are significantly downregulated supporting the idea that STING degradation through autophagy attenuates the expression of type I IFN genes, thereby promoting cancer cell progression." (PMID 38660307, 2024). "Reduced TFAM and mtDNA levels lead to decreased mitochondrial activity, and the TFAM-mediated regulation of various cancers’ carcinogenicity may occur through the disruption of LC3 II-mediated autophagy." (PMID 38247538, 2024). "The function of TFAM in carcinogenesis is controversial in different cancer types." (PMID 38429817, 2024). "Due to the heterogeneity and complexity of tumors, TFAM may exhibit different functions and regulatory mechanisms in different types of cancer." (PMID 38589371, 2024). "The roles of PGC-1α/NRF1/2/TFAM in human cancers are still under investigation." (PMID 39273403, 2024). "Moreover, dysregulation of mitochondrial transcription factors, such as POLRMT, TFAM, TFB2M, and MTERFs, has been implicated in cancer development and progression." (PMID 38589371, 2024). "Therefore, further research is needed to better understand the specific roles and molecular mechanisms of TFAM in specific types of cancer." (PMID 38589371, 2024). "Different levels of TFAM expression have been reported in cancers." (PMID 39273403, 2024). "Our research suggested that targeting TFAM could be an effective approach to enhance the sensitivity of cancer patients to sorafenib, and OA might be a promising anti-cancer agent, especially in a hypoxic microenvironment." (PMID 39770569, 2024). "Since TFAM affects the energy levels in cells, it is not surprising that the protein has been linked to changes in the tumorigenesis of cancer cells." (PMID 39580766, 2024). "Likewise, we found that the GAC cancer cell line had a higher migration activity while expressing higher HK-II and lower mtDNA copy numbers after an obvious TFAM knockdown." (PMID 35163779, 2022).
cancer (continued). "The PGC-1α /TFAM axis plays a critical role in energy metabolism and mitochondrial biogenesis, and the members of this axis are expressed at high levels in cancer as a result of the abundance of mitochondria, active oxidative metabolism and response to increased energy needs." (PMID 34906113, 2021). "Interestingly, persistent mtDNA stress in TFAM-deficient mouse melanoma cells contributes to chemotherapy drug resistance in vitro and in vivo, suggesting that suppression of mtDNA damage and release might be a potential target to prevent cancer chemoresistance." (PMID 34445229, 2021). "TFAM expression does not have the same effect on the prognosis of all types of TFAM-associated cancers." (PMID 32824374, 2020). "Under normoxia, mitochondrial metabolism in cancer cells may be favored because mTOR triggers mitochondrial biogenesis through TFAM and PGC1-α activation; in addition, mTOR may upregulate glycolysis through HIF-1α activation." (PMID 31600993, 2019). "This indicated that TFAM might be a potential target for increasing the sensitization of cancer cells to radiotherapy." (PMID 31062473, 2019). "Our results provided information about how mitochondria affected cellular oxidative stress and suggested that TFAM might be a sensitizing target in cancer radiotherapy." (PMID 31062473, 2019). "Whereas this evidence suggests that depleted or enriched TFAM parallels changes in mtDNA and might be specific of certain cancer types, further investigation is needed to evaluate the influence of TFAM mutations in HCC development and progression." (PMID 29137431, 2017). "It is of interest to note the effect of TFAM knockdown on the stemness of cancer cells." (PMID 27231905, 2016). "Furthermore, overexpression of TFAM (mitochondrial transcription factor A) leads to increased mitochondrial biomass and stimulates cell proliferation of cancer cells." (PMID 26580606, 2015). "Alterations in TFAM expression may serve as a potential marker to reflect Warburg effect in cancer." (PMID 41398603, 2025). "With this same mitoepigenetics approach, some researchers are linking TFAM not only to nDNA methylation but also to mitochondrial nucleoid alterations (either by depletion, overexpression, or post-translational modifications) that may be cancer-related." (PMID 35054416, 2021). "Thus, we speculate TFAM depletion and other mitochondrial dysfunction may induce different metabolic programs depending on cancer types." (PMID 29259235, 2017). "Notably, the expression of miRNA-159-3p and TFAM in cancer tissues was shown to be negatively correlated, which indicated that miRNA-159-3p may inhibit the expression of TFAM." (PMID 24137381, 2013). "Furthermore, the tissues of the various cancer stages showed differing expression levels of TFAM." (PMID 24137381, 2013). "We did not notice considerable differences in the transcript content for PGC-1α, TFAM and COX4/1 in cancer tissue." (PMID 36012230, 2022). "As enhanced metastatic activity and drug resistance are also hallmarks of cancer cells, cell motility and chemotherapeutic sensitivity was next assessed in HNC cells differentially expressed TFAM." (PMID 34663785, 2021). "Finally, we characterized a novel TFAM downstream pathway that may provide mechanistic insight into cell differentiation and proliferation, and contribute to the rational development of new prognostic and therapeutic tools for cancer treatment." (PMID 29259235, 2017). "Previous studies have shown that TFAM knockdown in BRCA cells enhances sensitivity to cisplatin, suggesting that TFAM may play a pro‐cancer role in BRCA." (PMID 40583735, 2025). "The anti-cancer effect is exerted via Akt-PGC1α-TFAM-mitochondria biogenesis signaling that reprograms cancer cell metabolisms prone to mitochondrial OXPHOS respiration and ROS production, and subsequently cancer cell apoptosis." (PMID 38702818, 2024).